UBE3A (ubiquitin protein ligase E3A)
Diseases named in the same sentence as UBE3A in open-access papers (continued):
Sharing a sentence is not in itself a finding about the gene and the disease.
Angelman syndrome (continued). "Various mutations including the gain of function mutations, triplication, or duplication in the UBE3A gene are also associated with various ASDs like Angelman Syndrome (AS) and Duplication 15q Syndrome (Dup15Q Syndrome)." (PMID 38248358, 2023). "Genetically decreased Arc expression additionally reduces abnormal EEGs and seizures in mice with Angelman syndrome associated with UBE3A gene-deficient function, because both Arc and UBE3A regulate surface expression of AMPA receptors." (PMID 37483450, 2023). "UBE3A’s functional loss in the brain leads to the development of Angelman Syndrome (AS), a sophisticated neuronal disease primarily affecting the neuronal system." (PMID 38248358, 2023). "Angelman syndrome (AS) is a severe neurodevelopmental disorder (NDD) caused by loss of functional ubiquitin protein ligase E3A (UBE3A)." (PMID 36810252, 2023). "Brain organoids can be used to study a specific disorder, such as Angelman syndrome (AS), a form of autism spectrum disorder caused by a loss-of-function mutation of the UBE3A gene." (PMID 37569905, 2023). "Angelman syndrome (AS) is a rare genetic neurodevelopmental disorder caused by the maternally inherited loss of function of the UBE3A gene." (PMID 36991133, 2023). "The majority of Angelman syndrome cases are caused by deletions which lead to a decrease in expression of UBE3A, the remaining due to mutations in UBE3A, paternal uniparental disomy (pUPD) and imprinting defects." (PMID 36710277, 2023). "BK channels are degraded by the ubiquitin ligase UBE3A, mutations in which cause Angelman’s syndrome." (PMID 35266450, 2022). "Angelman syndrome (AS) is a severe neurodevelopmental disorder caused by the loss of neuronal E3 ligase UBE3A." (PMID 35264729, 2022). "Angelman syndrome (AS) is a neurodevelopmental disorder caused by deficits in maternally inherited UBE3A." (PMID 36139390, 2022). "Angelman syndrome is a neurodevelopmental disorder caused by deficiency of the maternally inherited UBE3A gene in neurons." (PMID 35611307, 2022). "Several Top2 inhibitors were found to reactivate the dormant allele of the autism and Angelman syndrome gene Ube3a in primary cortical neurons from mice by reducing the transcription of an imprinted antisense RNA, Ube3a-ATS." (PMID 36417527, 2022). "For example, in Angelman syndrome, insufficiency of ubiquitin protein ligase E3A (UBE3A) caused by mutations in maternally inherited allele can be rescued by de-repression of the imprinted paternal copy." (PMID 36250017, 2022). "Angelman syndrome (AS) is a rare neurodevelopmental disorder caused by mutation or loss of UBE3A and marked by intellectual disability, ataxia, autism‐like symptoms, and other atypical behaviors." (PMID 34985196, 2022). "In an Angelman syndrome organoid model, the mechanism of synaptic dysfunction caused by ubiquitin protein ligase E3A (UBE3A) was illuminated." (PMID 35495031, 2022). "Angelman syndrome (AS) is a neurodevelopmental disorder caused by the loss of function of the E3-ligase UBE3A." (PMID 36012404, 2022). "The Ube3A mutation can cause the Angelman syndrome, a neurological disease accompanied by severe developmental delay, hypotonia, epilepsy, aphasia, and other complications." (PMID 35309141, 2022). "Both too little, and too much, E3 ligase activity can result in seizures, as seen in the UBE3A-implicated genetic disorders Dup15q and Angelman syndrome." (PMID 35327449, 2022). "Angelman syndrome (AS) is a neurodevelopmental disorder caused by loss of expression of the maternal copy of the UBE3A gene." (PMID 36192373, 2022). "Angelman syndrome (AS) is a neurodevelopmental disorder caused by loss‐of‐function mutations in the maternal copy of the UBE3A gene." (PMID 35304979, 2022).
Angelman syndrome (continued). "Loss of functional UBE3A gene expression is the principal reason for and cause of Angelman syndrome." (PMID 36011358, 2022). "To elucidate the molecular mechanisms associated in AS with loss of function of the UBE3A protein, we analyzed the publicly available RNA sequencing (RNA-seq) and DNA methylation (bisulfite-seq) data of Angelman syndrome patients." (PMID 36012404, 2022). "Although UBE3A deficiency indisputably leads to Angelman syndrome, a causal connection between UBE3A overexpression and Dup15q syndrome phenotypes has proved elusive." (PMID 36134658, 2022). "Such diversity of functional effects of missense variants has already been shown for other NDDs, for example for TCF4 variants causing Pitt-Hopkins syndrome (MIM #610 954) or variants in UBE3A causing Angelman syndrome (MIM #105 830)." (PMID 34505148, 2022). "Angelman syndrome is a neurodevelopmental disease caused by the loss of function of maternal inherited UBE3A, while paternal UBE3A remains intact." (PMID 33995501, 2021). "Here, we review the Angelman Syndrome, the causal gene, UBE3A, animal models of AS, emerging genetic, stem cell and precision medicine therapies and associated challenges faced in bench to bedside pipeline." (PMID 34528170, 2021). "Mice carrying the Q588E mutation exhibit aberrant early-life motor and communication deficits, and individuals possessing hyperactivating UBE3A variants exhibit affected phenotypes that are distinguishable from Angelman syndrome." (PMID 34815418, 2021). "UBE3A-deficient rats showed signs similar to what have been observed in patients with Angelman syndrome, namely cognitive and motor impairment." (PMID 33791256, 2021). "For instance, to facilitate the study on how the loss of UBE3A, which regulates synaptic development, in neurons leads to Angelman syndrome, in vitro and in vivo (rat) models were generated by knocking out UBE3A using CRISPR." (PMID 33791256, 2021). "Researchers have identified loss-of-function mutations of maternal UBE3A in 8% Angelman syndrome (AS) cases." (PMID 33995501, 2021). "One case with single focal seizures was associated with a heterozygous microdeletion of the UBE3A gene—Angelman syndrome." (PMID 34177756, 2021). "The most common cause for Angelman Syndrome (AS) is the loss of UBE3A in mature neurons due to a deletion of the maternal UBE3A allele and silencing of the paternal allele via a long non-coding RNA." (PMID 35153670, 2021). "As the animal model of the Angelman syndrome, 2 to 3 month old male and female Ube3a maternal deficient and knock-out mice were used." (PMID 34067192, 2021). "Angelman syndrome (AS) is a rare neurodevelopmental disease that is caused by the loss of function of the maternal copy of ubiquitin–protein ligase E3A (UBE3A) on the chromosome 15q11–13 region." (PMID 34203304, 2021). "Here, we develop a large-scale assay to characterize the functional valence (gain or loss-of-function) of missense variants identified in UBE3A, the gene whose loss-of-function causes the neurodevelopmental disorder Angelman syndrome." (PMID 34815418, 2021). "Angelman syndrome (AS) is a severe neurodevelopmental disorder caused by brain-specific loss of UBE3A, an E3 ubiquitin protein ligase." (PMID 33542309, 2021). "Angelman syndrome, caused by ubiquitin protein ligase E3A (UBE3A) LOF, is a complex neurodevelopmental disease characterized by epilepsy, developmental regression, and autistic features." (PMID 33616084, 2021). "Since the original reports associating UBE3A with Angelman syndrome in 1997, approximately forty-five further genes coding for E3 ubiquitin ligases or CRL substrate receptors have been identified as causative genes for forty-eight different forms of NDD." (PMID 34566579, 2021). "In humans, loss-of-function mutations in the UBE3A gene lead to the neurodevelopmental disorder Angelman syndrome (AS)." (PMID 34593829, 2021).
Angelman syndrome (continued). "Most recently, CRISPR-Cas9 gene therapy was used to “un-silence” the dormant paternally inherited UBE3A allele during the prenatal and early postnatal period, rescuing the expected anatomical and behavioral phenotypes associated with Angelman syndrome." (PMID 34654371, 2021). "Small molecule activators that rescue the E3 ligase activity of wild-type as well as Angelman syndrome variants of Ube3A/E6AP have been identified." (PMID 34867205, 2021). "Mutations or deletions of maternal UBE3A, leads to loss of UBE3A in neurons and Angelman syndrome (AS), a severe neurodevelopmental disorder characterized by delayed development, speech impairment, ataxia, and intellectual disability." (PMID 33737669, 2021). "UBE3A-ATS is a nuclear lncRNA that has been implicated in Angelman syndrome (AS), a severe neurodevelopmental disorder caused by a maternal deficiency of the imprinted gene UBE3A." (PMID 34349622, 2021). "For example, approximately 11% of cases of Angelman syndrome are due to pathogenic sequence variants in the UBE3A gene." (PMID 34071827, 2021). "The Ube3a deficiency mouse was used as the animal model of Angelman syndrome, and a behavioral defect in fluid consuming activity was seen in maternally inherited Ube3a deficiency (Ube3am−/p+)." (PMID 34067192, 2021). "Another largely monogenic rare genetic epilepsy syndrome is that of Angelman syndrome which is most often caused by LoF mutations in the maternal UBE3A gene encoding ubiquitin-protein ligase E3A." (PMID 34690692, 2021). "Loss of the maternal UBE3A allele causes Angelman syndrome (AS), a debilitating neurodevelopmental disorder." (PMID 34676830, 2021). "Lack of UBE3A protein expression leads to Angelman syndrome (AS), while its overexpression is associated with autism." (PMID 32455880, 2020). "Knockdown of Ube3A, an E3 ligase, was found to reduce dendritic arborization in Drosophila neurons, and mutations of Ube3A are associated with Angelman Syndrome (AS), discussed in section “Protein Degradation and Disease”." (PMID 33013325, 2020). "Lack of UBE3A causes a severe neurodevelopmental disorder known as Angelman syndrome (AS), while overexpression of UBE3A, as in the case of 15q duplication (dup15q), leads to severe autism." (PMID 32532103, 2020). "The systemic injection of TAT-S1-linked UBE3a-6ZF-KRAB repressor partially rescued Ube3a expression levels in the hippocampus and cerebellum of a mouse model of Angelman syndrome." (PMID 33192264, 2020). "The ubiquitin ligase, Ube3a, plays important roles in brain development and functions, since its deficiency results in Angelman Syndrome (AS) while its over-expression increases the risk for autism." (PMID 32555345, 2020). "In humans, the loss of maternally expressed Ubiquitin protein ligase E3A (UBE3A) is a cause of Angelman Syndrome (AS), a neurodevelopmental disorder." (PMID 32877400, 2020). "Functional loss of the UBE3A protein causes Angelman syndrome, another rare genetic NDD whose clinical features (e.g., ID and epilepsy) and etiology (e.g., UBE3A dysfunction) partially overlap with Dup15q syndrome." (PMID 32791992, 2020). "Deletion or loss-of-function mutations in human UBE3A gene are associated with Angelman syndrome (AS), while duplication of the chromosomal region (15q11–13) containing UBE3A has been discovered in 1.0–3.0% familial ASD (Autism Spectrum Disorders) worldwide." (PMID 32545848, 2020). "Angelman syndrome is a neurological disorder caused by a genetic UBE3A deficiency resulting in intellectual disability, ataxia and seizures." (PMID 33192264, 2020). "The malfunction of UBE3A on the maternal allele is known to cause Angelman syndrome, which is characterized by intellectual disability, ataxia, severe speech impairment, and other neurological and behavioral features." (PMID 32722525, 2020).
Angelman syndrome (continued). "Loss of expression of the ubiquitin-protein ligase E3a (UBE3A) is associated with most cases of Angelman syndrome, which is a rare syndrome of developmental delay, ID and ASD." (PMID 32982715, 2020). "Optimal CNS expression of UBE3A is crucial since its deficiency results in Angelman Syndrome (AS), while its over-expression increases the risk for autism." (PMID 32555345, 2020). "A mouse model of Angelman syndrome (AS), which lacks expression of the maternally inherited Ube3a allele, has deficits in synaptic function and experience-dependent plasticity in the primary visual cortex." (PMID 33076843, 2020). "Loss of UBE3A in neurons underlies Angelman syndrome (AS), and increased UBE3A gene dosage via duplications is associated with autism." (PMID 33076843, 2020). "It is well established that loss-of-function alterations of the UBE3A gene cause Angelman syndrome, a severe neurodevelopmental disorder with autosomal dominant inheritance modified by genomic imprinting on chromosome 15q." (PMID 32751183, 2020). "UBE3A gene encodes the E6-AP ubiquitin-protein ligase and is the causative gene in Angelman syndrome (AS), point mutations in UBE3A gene were discovered in about 10% cases of AS." (PMID 33308194, 2020). "Angelman syndrome (AS) is a rare neurodevelopmental disorder caused by the loss of functional ubiquitin protein ligase E3A (UBE3A)." (PMID 32948244, 2020). "Angelman syndrome is caused by maternal deficiency of UBE3A, with the paternal copy of UBE3A being silenced by a lncRNA named UBE3A‐ATS." (PMID 30456884, 2019). "Most cases of Angelman syndrome are caused by loss-of-function mutations in the maternal allele of the imprinted UBE3A gene, the gene product of which carries a HECT domain driving ubiquitylation to mediate substrate degradation by the proteasome." (PMID 31438473, 2019). "Another syndromic form of ASD is Angelman syndrome (AS), a severe neurodevelopmental disorder caused by a mutation or deletion of the maternal UBE3A allele." (PMID 31807945, 2019). "Ubiquitin protein ligase E3A (Ube3a), a causative gene product of Angelman’s syndrome, is involved in the acidification of the Golgi lumen." (PMID 31118204, 2019). "Many cases of Angelman syndrome are caused by loss-of-function mutations in the maternal allele of the imprinted Ubiquitin-protein ligase E3A (UBE3A) gene." (PMID 31438473, 2019). "For example, the ubiquitin ligase gene UBE3A is implicated in both autism and Angelman Syndrome, a condition distinct from ASD but with similar symptoms, such as movement and speech defects." (PMID 31481879, 2019). "Angelman syndrome (AS) is a severe neurodevelopmental disorder caused by mutations affecting UBE3A gene expression." (PMID 31143434, 2019). "The expression of ubiquitin ligase UBE3A is paternally imprinted in neurons and loss of function of maternally inherited UBE3A causes Angelman syndrome (AS), a neurodevelopmental disorder characterized by severe intellectual disability and motor disturbances." (PMID 30814928, 2019). "While a loss-of-function mutation in UBE3A underlies Angelman’s syndrome, gain-of-function mutations of UBE3A are also associated with autistic features." (PMID 31807945, 2019). "90% of these lncRNAs are oriented in or around known genes related to neurodevelopmental and psychiatric diseases, such as UBE3A (ubiquitin protein ligase E3A), which is associated with Angelman syndrome, that shares common features with ASD." (PMID 30728830, 2018). "The loss of UBE3A function causes Angelman syndrome (AS), characterized by profound intellectual and developmental disabilities." (PMID 30364390, 2018). "Angelman syndrome (AS) is a neurodevelopmental disorder caused by mutations affecting UBE3A function." (PMID 30220990, 2018). "HECT E3s are directly implicated in cancer, hypertension, neurodegenerative disorders, and other diseases, such as Angelman syndrome which is caused by the loss of maternally inherited UBE3A." (PMID 29858610, 2018).
Angelman syndrome (continued). "Loss of UBE3A causes Angelman syndrome, whereas excess UBE3A activity appears to increase the risk for autism." (PMID 30364390, 2018). "UBE2H enzyme is associated with autism and loss of Parkin and UBE3A ligase activity is linked to autosomal recessive juvenile parkinsonism and Angelman Syndrome, respectively." (PMID 29693004, 2018). "In 1997, it was shown that genetic alterations of the UBE3A gene, resulting in loss of E6AP expression or in the expression of E6AP variants with compromised E3 activity, are the cause of the Angelman syndrome (AS), a neurodevelopmental disorder." (PMID 30361475, 2018). "Abnormal mTORC1 activation has been implicated in several developmental neurological disorders, including Angelman syndrome (AS), which is caused by maternal deficiency of the ubiquitin E3 ligase UBE3A." (PMID 30020076, 2018). "A female proband with Angelman syndrome has a variant in gene UBE3A inherited from her healthy mother." (PMID 29720203, 2018). "UBE3A, an E3 ligase in the ubiquitin-proteasomal system, plays important roles in brain development and normal function, as UBE3A deficiency results in Angelman syndrome (AS), while UBE3A over-expression increases the risk for autism." (PMID 30020076, 2018). "Both Parkin (PARK2) and UBE3A are E3 ubiquitin ligases for which mutations result in severe brain dysfunction, Familial Parkinson's Disease (PD), and Angelman Syndrome (AS)." (PMID 29693004, 2018). "Located at the N terminus (residues 24–87), E6AP harbors a zinc-binding fold called the AZUL (amino-terminal Zn-finger of Ube3a ligase) domain of which mutations have been associated with Angelman syndrome." (PMID 29858610, 2018). "Loss-of-function or loss-of-expression of the maternally inherited UBE3A allele causes Angelman syndrome (AS), which presents with intellectual disability, ataxia, epilepsy, sleep disorders, and an atypical ‘happy’ disposition." (PMID 28515788, 2017). "Mitochondrial dysfunction observed in hippocampal neurons of the UBE3A-deficient mouse model of Angelman syndrome." (PMID 28270747, 2017). "Angelman syndrome (AS) is a neurogenetic disorder caused by deletion of the maternally inherited UBE3A allele and is characterized by developmental delay, intellectual disability, ataxia, seizures and a happy affect." (PMID 28436452, 2017). "Five patients had pathogenic mutations in the TCF4 gene and one in the UBE3A gene, which are associated with Pitt-Hopkins syndrome and Angelman syndrome, respectively." (PMID 28947817, 2017). "Our String analysis puts the ubiquitin system (UBC) in a central point for ADNP regulatory pathways, and in that respect, Angelman syndrome is caused by ubiquitin protein ligase E3A mutations." (PMID 28221363, 2017). "Angelman syndrome (AS) is a neurodevelopmental disorder that results from deletions or mutations in chromosome 15, which usually includes the UBE3A gene." (PMID 28804447, 2017). "Angelman syndrome (AS) is a genetic neurodevelopmental disorder, most commonly caused by deletion or mutation of the maternal allele of the UBE3A gene, with behavioral phenotypes and seizures as key features." (PMID 28814801, 2017). "Ubiquitin protein ligase E3A (UBE3A) is the causative gene for Angelman syndrome, a developmental disorder characterized by language impairments, ataxia, ID and hyperactivity." (PMID 29209173, 2017). "Synaptic plasticity has been studied in great detail in the UBE3A maternally deficient mice, the Angelman syndrome mouse model." (PMID 29209173, 2017). "Mutations or deletions of the maternal allele of the UBE3A gene cause Angelman syndrome (AS), a severe neurodevelopmental disorder." (PMID 27306933, 2016).